MTA1 (metastasis associated 1)
Diseases named in the same sentence as MTA1 in open-access papers (continued):
Sharing a sentence is not in itself a finding about the gene and the disease.
breast carcinoma (continued). "MTA1 was first discovered as a gene related to tumor metastasis in breast cancer, and more of its biological function was revealed in subsequent studies." (PMID 35350571, 2022). "We transfected Si-FOXP3 and Si-MTA1 into MCF-7 breast cancer cells and determined the mRNA expression levels of the selected potential downstream molecules of MTA1 through real-time PCR." (PMID 34307133, 2021). "In breast cancer cells, O-GlcNAcylation of MTA1 promotes the expression of genes involved in adaptation of breast cancer cells to genotoxic stress." (PMID 35201498, 2021). "Combined with the results of previous in vitro and in vivo experiments, these results demonstrated that FOXP3 can hinder breast cancer metastasis by downregulating MTA1 expression." (PMID 34307133, 2021). "To further verify the correlation between FOXP3 and MTA1 expression in breast cancer, we downloaded and analysed breast cancer case data from public databases." (PMID 34307133, 2021). "To explore the clinical significance of FOXP3 and MTA1 expression in the development of breast cancer, we evaluated FOXP3 and MTA1 expression in 92 breast cancer tissues." (PMID 34307133, 2021). "In summary, through in vitro cell assays, in vivo animal experiments, and analysis of clinical breast cancer samples, we systematically confirmed the regulation of MTA1 expression by FOXP3 and clarified its mechanism." (PMID 34307133, 2021). "Then, we confirmed that FOXP3 can inhibit the expression of MTA1 by binding to the promoter of MTA1 and thus reduce the ability of breast cancer cells to metastasize." (PMID 34307133, 2021). "Our experiment revealed that MTA1 is a new target gene of FOXP3 that regulates breast cancer metastasis and provides further knowledge about the mechanism of FOXP3 in breast cancer metastasis." (PMID 34307133, 2021). "FOXP3 downregulated the expression of MTA1 in breast cancer cells by directly inhibiting MTA1 promoter activity." (PMID 34307133, 2021). "The results showed that the expression level of FOXP3 in the nucleus was negatively correlated with lymph node metastasis from breast cancer and pathological stage, while the expression level of MTA1 was positively correlated with these parameters." (PMID 34307133, 2021). "Immunohistochemistry was adopted to explore the correlation between the expression levels of FOXP3 and MTA1 in breast cancer samples." (PMID 34307133, 2021). "This pattern suggests that FOXP3 regulates the expression of downstream molecules in addition to MTA1 to inhibit breast cancer metastasis." (PMID 34307133, 2021). "Analysis of 1166 breast cancer patients in The Cancer Genome Atlas (TCGA) database and breast cancer case data in GEPIA showed that the FOXP3 expression level was negatively correlated with the MTA1 expression level, consistent with our results." (PMID 34307133, 2021). "On this premise, we verified that FOXP3 expression and MTA1 expression were negatively correlated in breast cancer tissues." (PMID 34307133, 2021). "A previous study shows that up-regulated expression of MTA1 leads tamoxifen resistance by promotion of autophagy in breast cancer." (PMID 33282725, 2020). "In ER+ breast cancer patients treated with tamoxifen, MTA1 expression increases in relapsed or recurrent disease and correlates with low disease free survival." (PMID 32878084, 2020). "For further verification, our study performed a tunnel assay, through which we got the same results that MTA1 knockdown endows a powerful chemotherapeutic sensitivity for GEM in luminal-b breast cancer cells." (PMID 33282725, 2020). "We also found that the mRNA levels of MTA1-3 are up regulated in basal_like type, Her2 type, luminal_a type and luminal-b type breast cancer tissue, when compared with normal tissues (p<0.05)." (PMID 33282725, 2020). "In this paper, our research shows that higher expression of MTA1 accompanies with worse prognosis in luminal-b breast cancer." (PMID 33282725, 2020).
breast carcinoma (continued). "The metastasis-associated protein (MTA) family, containing MTA1, MTA1s, MTA1-ZG29p, MTA2, MTA3, and MTA3L, is famous for its member MTA1 which is first isolated from a metastatic breast cancer cell." (PMID 33282725, 2020). "In this study, we apply the TCGA database and clinical samples to analyze the relationship between MTA1 level and disease progression in luminal-b type breast cancer." (PMID 33282725, 2020). "Surprisingly, in our study, we found that MTA1 overexpression significantly inhibited the metastasis of ZR-75-30 luminal B breast cancer cells." (PMID 30642362, 2019). "Definitive evidence of exosome MTA1 transfer was obtained using a co-culture model system in which a florescent-tagged MTA1 was expressed in breast cancer cells and transferred to breast cancer cells and endothelial cells." (PMID 30782165, 2019). "This is the first study to have identified the nuclear factor MTA1 in breast cancer exosomes, demonstrated the transfer of MTA1 through exosomes, and characterized how exosome MTA1 affects cancer signaling pathways." (PMID 30782165, 2019). "We demonstrated that MTA1 can be transferred via exosomes from breast cancer cells to neighboring cells and can activate or repress signaling pathways that are known to promote cancer progression." (PMID 30782165, 2019). "The results showed that MTA1 played different roles in the migration and invasion of different breast cancer cells in vitro." (PMID 30642362, 2019). "As the first member of the metastasis-associated protein (MTA) family, MTA1 and another MTA family member, MTA2, have both been reported to promote breast cancer progression and metastasis." (PMID 30642362, 2019). "The transfer of MTA1 through breast cancer exosomes was initially revealed by a well-designed antibody array and confirmed by western blot analysis that detected MTA1 expression in exosomes derived from breast cancer cells." (PMID 30782165, 2019). "Similar to the seemingly contradictory roles of MTA1, the residual expression of elafin in invasive breast cancer predicts a significantly poor prognosis of breast cancer patients: a tumor suppressor gene turned into an oncogene." (PMID 30642362, 2019). "The overexpression of MTA1 has been shown to downregulate the expression of MTA2 at the protein level instead of by transcriptional repression in breast cancer cells." (PMID 30642362, 2019). "Given the significance of hypoxic signaling in breast cancer, this observation strongly suggests an important role of exosome MTA1 in breast cancer progression." (PMID 30782165, 2019). "Consistent with its co-activator function, exosome MTA1 was able to increase hypoxia signaling in breast cancer cells as analyzed by a reporter gene assay." (PMID 30782165, 2019). "Overall, our study provided direct evidence for the different roles that MTA1 and MTA2 play in breast cancer cell metastasis and clarified the mechanism by which MTA1 downregulates MTA2 at the protein level." (PMID 30642362, 2019). "To investigate the role of MTA1 in luminal B breast cancer metastasis, we first established two stable cell lines, ZR-75-30-MTA1 overexpressing MTA1 and ZR-75-30-Vector as a control." (PMID 30642362, 2019). "We identified MTA1 in BC exosomes by antibody array and confirmed expression of exosome-MTA1 across five breast cancer cells lines." (PMID 30782165, 2019). "It has been reported that MTA1 exhibited different expression and distribution patterns during the development of breast cancer in a mouse model, implying that the roles of MTA1 are altered sequentially." (PMID 30642362, 2019). "This work suggests that exosome-mediated transfer of MTA1 is a significant driving force behind breast cancer progression and that targeting exosome MTA1 signaling or activity are potential therapeutic strategies for breast cancer management." (PMID 30782165, 2019). "Cell proliferation was significantly reduced in each MTA1 knockout breast cancer cell line relative to wildtype control cells." (PMID 30782165, 2019).
breast carcinoma (continued). "In a trans-well co-culture system exosome-mediated transfer of MTA1 from MCF7 and MDA-MB-231 cells expressing GFP-CD63 and tdTom-MTA1 to ZR-75-1 (breast cancer cells) and EA.hy926 (vascular endothelial cells) was observed by fluorescent microscopy." (PMID 30782165, 2019). "The target cells used in this assay were the colon cancer cell lines SW620 (HLA-A∗0201+, MTA1+) and HT-29 (HLA-A2−, MTA1+) and the breast cancer cell line MDA-MB-231 (HLA-A∗0201+, MTA1+)." (PMID 30596107, 2018). "We found that MTA1 overexpression results in a marked reduction in the level of DNMT3a, while MTA1 silencing leads to an increased DNMT3a expression in breast cancer MCF-7 and SKBR-3 cells." (PMID 28393842, 2017). "High levels of MTA1 and high levels of IGFBP3 associates with a poor relapse-free and metastasis-free survival of breast cancer patients." (PMID 28393842, 2017). "This in vivo experiment was done on 263 surgical specimens of breast cancer cases and IHC was performed to know the MTA1 expression level." (PMID 29254284, 2017). "Here, we found an inverse relationship between the levels of MTA1 and DNMT3a in human cancer and that high levels of MTA1 in combination of low DNMT3a status correlates well with poor survival of breast cancer patients." (PMID 28393842, 2017). "Together findings presented here recognize an inherent role of MTA1 as a modifier of DNMT3a and IGFBP3 expression, and consequently, the role of MTA1-DNMT3a-IGFBP3 axis in breast cancer progression." (PMID 28393842, 2017). "We first analyzed the level of secreted IGFBP3 and cellular IGFBP3 in MCF-7 and MTA1 overexpressing breast cancer cells." (PMID 28393842, 2017). "To experimentally validate the noticed, presumed negative regulation of DNMT3a expression by MTA1, we selected breast cancer model system for subsequent studies." (PMID 28393842, 2017). "Similar to breast cancer cells, MTA1 silencing or overexpression in HCT116 colon cancer cells also leads to upregulation or downregulation of DNMT3a, respectively." (PMID 28393842, 2017). "Like Oncomine datasets, we also found an inverse relationship between the status of MTA1 and DNMT3a mRNAs in 971 cases of breast cancers from the TCGA dataset analyzed using cBioPortal tools." (PMID 28393842, 2017). "To assess the clinical significance of MTA1/DNMT3a/IGFBP3 axis in breast cancer, we performed a two-way correlation involving low levels of DNMT3a and high levels of IGFBP3 associated with a poor distant metastasis-free survival." (PMID 28393842, 2017). "First, we examined the effect of overexpression or depletion of MTA1 on the status of DNMT3a in breast cancer cells." (PMID 28393842, 2017). "We found that the levels of MTA1 and DNMT3a are inversely correlate in human cancer at-large, and that low DNMT3a in combination of high MTA1 expression predicts a poor clinical outcome in breast cancer patients." (PMID 28393842, 2017). "It was interesting to see that Z-LIG not only reduced the MTA1 expression in the three ERα− breast cancer cells, but also decreased the recruitment of MTA1 to the ERα promoter region in MDA-MB-231 cells." (PMID 28415616, 2017). "MTA1 enhances lung metastasis of breast cancer by upregulating STAT3 transcription, which promotes cell survival, angiogenesis, invasion and metastasis." (PMID 26968810, 2016). "MTA1 has been reported to promote lung metastasis of breast cancer by stimulating STAT3 transcription and the expression of STAT3 target genes." (PMID 26968810, 2016). "In estrogen receptor-positive breast cancer cells, MTA1 suppresses the estrogen-receptor element-driven transcription and disrupts estradiol responsiveness, thus contributing to progression of breast cancer to more invasive phenotypes." (PMID 25644400, 2015). "Prominently, MTA1 enhances the ability of cancer cell invasion and metastasis in breast cancer and some other cancers." (PMID 25644400, 2015).
breast carcinoma (continued). "Inhibition of Stat3 via si-Stat3 or Stattic treatment also potentiated HNK-mediated inhibition of MTA1 and β-catenin expression in breast cancer cells." (PMID 26036628, 2015). "Treatment of breast cancer cells with leptin exhibited striking increase in MTA1, Wnt1, β-catenin and cyclin D1 expression in comparison to untreated cells." (PMID 26036628, 2015). "A reduced rate of breast cancer metastasis to lung was observed in the MTA1 null genetic background." (PMID 25332145, 2014). "The first factor known to be able to stimulate MTA1 expression in breast cancer cells is the growth factor heregulin." (PMID 25332145, 2014). "MTA1 controbutes to inappropriate development of mammary glands, hyperplastic nodules and mammary tumors." (PMID 23941622, 2013). "MTA1 was originally identified by differential cDNA screening using highly metastatic breast cancer cell lines." (PMID 23227138, 2012). "For example, coactivators like SRC-1, amplified in breast cancer (AIB1), and CBP have been shown to possess histone acetyltransferase activity, whereas corepressors, such as NCOR and MTA1, are associated with histone deacetylases." (PMID 22295247, 2012). "For example, MTA1, a commonly deregulated coregulator in breast cancer, promotes transcriptional repression of ER, leading to metastatic progression." (PMID 22295247, 2012). "Dysregulation of HER2 in breast cancer cells enhances the expression of an isoform of MTA1 (MTA1s), which promotes the cytoplasmic sequestration of ERα leading to constitutive activation of MAPK." (PMID 22295247, 2012). "ShRNA expression vectors targeting MTA1 was constructed and transfected into human breast cancer cell lines MDA-MB-231 and MCF-7." (PMID 21595884, 2011). "We found that both Aw551984/VWA5A were negatively regulated by Mta1 in MEFs and human breast cancer cells." (PMID 21364872, 2011). "Overexpression of MTA1 plays an important role in tumorigenesis and tumor aggressiveness, especially tumor invasiveness and metastasis, including breast cancer." (PMID 21595884, 2011). "The effects of inhibiting MTA1 gene on invasion of breast cancer cells were evaluated by Boyden chamber migration assay." (PMID 21595884, 2011). "Here, we successfully transfected two shRNAs targeting MTA1 gene into human breast cancer cell lines MDA-MB-231 and MCF-7." (PMID 21595884, 2011). "In contrast to the results obtained here, stable expression of MTA1 in MCF-7 breast cancer cells resulted in a markedly enhanced ability of these cells to grow substrate-independently and to form large colonies in soft agar." (PMID 14735193, 2004). "TRIM21 is downregulated by MTA1 and plays a vital role in breast cancer." (PMID 39154024, 2024). "In this study, we investigated whether MTA1 is overexpressed in breast cancer tissues and whether it correlates with poor survival in patients with breast cancer." (PMID 39154024, 2024). "Patients with high MTA1 expression-breast cancer had poor prognosis." (PMID 39154024, 2024). "As a regulator of epithelial-mesenchymal transition, ZEB2 is strongly downregulated by miR-221, and ZEB2 expression was increased, which in turn inhibited the expression of G9A and MTA3 by recruiting G9A/NuRD (MTA1), thereby promoting the metastasis and progression of breast cancer." (PMID 36072677, 2022). "Taken together, our findings systematically confirmed that FOXP3 could inhibit breast cancer metastasis by regulating MTA1 expression, providing an experimental basis and new ideas for the treatment of metastatic breast cancer." (PMID 34307133, 2021). "Moreover, analysis of clinical specimens showed a significant negative correlation between the expression levels of FOXP3 and MTA1 in breast cancer." (PMID 34307133, 2021). "Furthermore, we analysed the correlation between FOXP3 and MTA1 expression in 92 breast cancer tissues." (PMID 34307133, 2021). "Importantly, FOXP3’s regulation of MTA1 affected the ability of breast cancer cells to invade and metastasize in vitro and in vivo." (PMID 34307133, 2021).
breast carcinoma (continued). "The expression of MTA1 in luminal-b breast cancer progression." (PMID 33282725, 2020). "However, the role of MTA1 in chemotherapeutic resistance in luminal-b breast cancer is still unclear." (PMID 33282725, 2020). "In our study, we found that the mRNA level of MTA1 is higher in breast cancer, as compared with normal tissue through TCGA debase analysis, and the clinical data showed that MTA1 was up-regulated in samples among the clinical stage-III/IV, when compared with samples in stage-I/II." (PMID 33282725, 2020). "So, blocking the MTA1 may be a useful strategy to sensitize the chemotherapy effects in advanced breast cancer." (PMID 33282725, 2020). "Furthermore, in order to make possible the application of the MTA1 targeted treatment in luminal-b type breast cancer in clinic, our study generated siMTA1-loaded exosomes." (PMID 33282725, 2020). "In addition, overall survival analysis showed that MTA1 was a positive factor for breast cancer regression (p=0.0289)." (PMID 33282725, 2020). "In addition, a recent study implied that MTA1 overexpression also promoted the autophagy process, which lead tamoxifen resistance in luminal-b type breast cancer cell lines." (PMID 33282725, 2020). "Importantly, MTA1 was detected in exosomes derived from all 5 breast cancer cell lines including MCF7, ZR-75-1, MDA-MB-231, BT-20, and SK-BR-3 as analyzed by western blot." (PMID 30782165, 2019). "In order to understand whether exosome-MTA1 contributes to breast cancer progression/metastasis, genetic knockouts of MTA1 in MCF7 and MDA-MB-231 cells were generated using a CRISPR/Cas9 expression system carrying a small guide RNA (sgRNA) targeted to MTA1." (PMID 30782165, 2019). "In this study, we identified many proteins in breast cancer exosomes that may contribute to breast cancer progression and specifically characterized the process and biological consequence of exosome transfer of MTA1 in breast cancer cells." (PMID 30782165, 2019). "The results from the present study indicate that exosome MTA1 could contribute to breast cancer progression by regulating important signaling pathways and thus may serve as a therapeutic target for the management of this malignancy." (PMID 30782165, 2019). "Because of the role of MTA2 in breast cancer metastasis, we hypothesized it's the same reason for MTA1-induced metastasis inhibition." (PMID 30642362, 2019). "It has been recently reported that MTA1 enhances the transcriptional activity of HIF-1α in human breast cancer cells, but the relationship between MTA1 and HIF-1α in HCC is unknown." (PMID 28589145, 2017). "It is possible that the noted DNMT3a downregulation could be an effector event of MTA1 overexpression during breast cancer progression." (PMID 28393842, 2017). "In general, MTA1 level is upregulated in human breast cancer with aggressive phenotypes." (PMID 28415616, 2017). "It was found that MTA1 expression level was significantly increased in a variety of solid tumor, such as hepatocellular cancer, esophageal cancer, pancreatic cancer and breast cancer, and could facilitate tumor invasion and metastasis in these malignancies." (PMID 28418887, 2017). "There is a relatively high basal level of MTA1 in all these three ERα− breast cancer cells." (PMID 28415616, 2017). "HNK inhibits leptin-induced Wnt1, MTA1 and β-catenin expression in breast cancer cells." (PMID 26036628, 2015). "Moreover, forced expression of MTA1 nhanced the ability of breast cancer cell line MCF-7 to grow in an anchorage-independent manner." (PMID 23941622, 2013). "Antisense of MTA1 inhibited the growth of highly metastatic breast cancer cell lines." (PMID 23941622, 2013). "In this study, two shRNA plasmid vectors against MTA1, which could persistently generate siRNA inside cells, were constructed and transfected into the breast cancer cell lines MDA-MB-231 and MCF-7." (PMID 21595884, 2011).